CD40 (CD40 molecule)
Diseases named in the same sentence as CD40 in open-access papers (continued):
Sharing a sentence is not in itself a finding about the gene and the disease.
Sepsis (continued). "Another study suggested that anti-CD40 treatment increased the level of antiapoptotic protein Bcl-x(L) in splenic B and T cells as well as in thymic T cells, provided nearly complete protection against sepsis-induced lymphocyte apoptosis, and improved the prognosis of sepsis." (PMID 29780830, 2018). "We re-examined the response to ICI treatment in sepsis using PANscore and found that PD-1 was more expressed in the LowPANscore subgroup, while PD-L1, LAG3, TIGIT, TNFRSF9, CD40, IDO1 were expressed in the HighPANscore subgroup (P<0.05)." (PMID 38239341, 2023). "Recent studies have shown that CD40 and CD40L are significantly elevated in sepsis patients and model animals, which are closely related to the severity of sepsis." (PMID 36303116, 2022). "In contrast, no significant changes were found in the expression of CD39, CD40, and CD86 on γδ T cells in individuals with sepsis versus healthy individuals." (PMID 35020851, 2022). "The expression of some surface markers (e.g., MHC class II or CD40) increased on septic MLN DCs, indicating that these molecules engage in functionally activating mucosal DCs during sepsis." (PMID 31323786, 2019). "In addition, sepsis did not cause the change of CD40 and CD80 in the lung until 7 d after CLP." (PMID 25821827, 2015). "Other cell surface markers like CD40 and CD69 whose expression increases in severe sepsis and decreases with the resolution of sepsis were significantly up- regulated at early time points, and decreased at 18 h (data not shown)." (PMID 23009705, 2012). "Functional markers such as CD40, CD80, CD86, and MHC-II were significantly upregulated by DCs in animal sepsis models during the initial phase of sepsis, which is essential for the activation of T cells, while DCs downregulated the expression of surface molecules at the late stage of sepsis." (PMID 38816685, 2024). "It was found that the percentages of MHCII, CD40, CD80, and CD86 on surface of DCs obviously increased in the sepsis-induced ALI group when compared to the control and GTS-21-positive control mice group, and the increase in MHCII, CD40, and CD86 was reduced through GTS-21 intervention." (PMID 35125962, 2022). "Emerging studies have focused on the effects of CD40 and its ligand CD40L on the process of sepsis." (PMID 29780830, 2018). "In the course of sepsis, activated platelets and leukocytes may release high amounts of soluble CD154 from their surface that interacts with the CD40 expressed by TEC and other target cells." (PMID 20064258, 2010). "We show here that zoledronate readily induces upregulation of HLA‐DR, CD40 and CD64 on monocytes from both healthy controls and sepsis patients, which could be abrogated by neutralising the pro‐inflammatory cytokines interferon (IFN)‐γ and tumour necrosis factor (TNF)‐α in the cultures." (PMID 31606902, 2020). "Expressions of CD40, CD86, PD-1, PD-L1, TIM-3 and LAG-3 were not changed on B220+ lymphocytes after sepsis." (PMID 40155394, 2025). "Taken together with our results, these data suggest that bystander activation of T cells in an inflammatory environment in which CD40 and/or CD134 signals are present in the absence of cognate antigen may drive CXCR4 upregulation during sepsis." (PMID 29232699, 2017).
B-cell lymphomas (28 papers, 1998 to 2025). "Immunoprecipitation experiments confirmed the interaction of CD40 with Fas at the endogenous levels in a BJAB B-cell lymphoma cell line deficient for TRAILR2." (PMID 28182009, 2017). "It has been previously reported that LMP1 sequesters and binds TRAF3 more effectively than CD40 to regulate the NF-κB pathway in B-cell lymphoma cells." (PMID 39164228, 2024). "Recently, the novel CD19CAR-T cells incorporated with B-cell costimulatory molecules of CD79A/CD40 demonstrated superior antitumor activity in the B-cell lymphoma model compared with CD28 or 4-1BB." (PMID 36505428, 2022). "Activation of CD40-signaling contributes to the initiation, progression and drug resistance of B cell lymphomas." (PMID 36110848, 2022). "We contributed to this knowledge by showing that constitutive CD40-signaling in B cells induces B cell hyperplasia and finally B cell lymphoma development in transgenic mice." (PMID 36110848, 2022). "Dacetuzumab, a monoclonal anti-CD40 antibody reduced tumor bulk in a third of patients with B-cell non-Hodgkin lymphomas." (PMID 32521744, 2020). "Here, our results show that NF-κB activated B-cell lymphoma of the LMP1/CD40-expressing mouse model exhibited an immune escape gene signature involving expression of PD-L1 and PD-L2, which expression was co-clusterized with IL-10." (PMID 31382969, 2019). "In preclinical studies, a rat anti-mouse CD40 antibody showed remarkable therapeutic activity in the treatment of CD40+ B-cell lymphomas." (PMID 31547627, 2019). "With CD40 being expressed on various B-cell lymphomas and carcinomas (nasopharynx, bladder, cervix, kidney and ovary), there is a renewed interest in CD40/CD40L in the control of tumor growth, leading to the development of new therapeutic strategies." (PMID 25479079, 2014). "CD40-mediated inhibition of proliferation has also been observed in high grade B-cell lymphoma derived cell lines in vitro as well as in vivo, suggesting that cytotoxic antiCD40 therapy is a potential strategy for B-cell lymphoma." (PMID 23840967, 2013). "B-cell receptor (BCR) and co-receptor CD40 signaling is essential for normal B cells, and there is increasing evidence that signaling via BCR and CD40 plays an important role in the pathogenesis of B-cell lymphoma." (PMID 23072591, 2012). "In vivo targeting of CD40+ APCs with a vaccine consisting on the A20 murine B cell lymphoma Id chemically conjugated to an anti-CD40 antibody induced more efficient tumor protection than a classic vaccination with Id-KLH plus GM-CSF." (PMID 23162790, 2012). "Similarly, in hematological cancer (B cell NHL), CD40 engagement via dacetuzumab (humanised agonistic CD40 IgG1 mAb; alias: SGN-40) was tolerated well amongst patients." (PMID 38440738, 2024). "Similarly, transfecting B-cell lymphomas with a CD40-agonist aptamer SMG1-shRNA chimera inhibited NMD activity, due to SMG1 kinase knockdown, and improved survival of mice with B-cell lymphomas." (PMID 36979701, 2023). "Assuming that in humans TRAF2 and TRAF3 mutations occur in premalignant cells, they may contribute to the initiation of B cell lymphomas through a similar RelB-dependent mechanism as we describe here for LMP1/CD40 mice." (PMID 36110848, 2022). "Interestingly, only anti-CD40 agonistic Ab treatment showed a strong anti-tumor effect by activating cytotoxic T cells in a mouse B cell lymphoma transplantation model." (PMID 34209347, 2021). "This immunotherapeutic chimera resulted in efficient NMD-targeted inhibition in CD40-expressing B-cell lymphomas while providing optimal conditions for cancer immunotherapy; activation of antigen-presenting cells, enhancement of tumor antigenicity, and bone-marrow aplasia recovery." (PMID 30340426, 2018). "In B-cell lymphomas, the relationship between CD40, Fas and TRAILRs appears even more complicated." (PMID 28182009, 2017). "CD40 stimulation can also activate p38 in B-cell lymphoma cell lines." (PMID 23072591, 2012).
B-cell lymphomas (continued). "Since this mouse model substantially mimics the constitutive CD40-stimulation of B cells in a pathological situation in humans, we regarded it as a perfect tool to study the role of RelB and its regulated genes in the initiation and progression of B cell lymphomas." (PMID 36110848, 2022). "B-cell NHLs frequently express CD27/CD27L (TNFRSF7/TNFSF7), CD30 or CD30L (TNFRSF8 or TNFSF8), CD40 (TNFRSF5), and TNFRs/TNF positive (TNFRSF1 and 2/TNFSF2), but T-cell NHLs show expression of CD30, CD40L (TNFSF5), and TNFRs/TNF." (PMID 37240076, 2023). "Additionally, noteworthy genes, including IKZF2, CCL4, SAA1, and CD40, exhibited differential expression in the TCL group compared to the B-cell lymphoma (BCL) group." (PMID 39911484, 2024). "Recently, agonist anti-CD40 antibody and CD40L alone or in combination with other therapies have been shown to significantly reduce the growth of B cell lymphomas, breast and ovarian carcinomas, and several other solid tumors and prolong overall survival of patients." (PMID 37430270, 2023). "CD40 activates, among others, the non-canonical NF-ĸB signaling, which is constitutively activated in several human B cell lymphomas and is therefore presumed to contribute to lymphopathogenesis." (PMID 36110848, 2022). "Additionally, the antagonistic CD40 aptamer effectively blocked the CD40-CD40L interaction and reduced B cell lymphoma proliferation in vitro and in vivo." (PMID 28325295, 2017). "Thus, our data suggest that continuous activation of non-canonical NF-ĸB signaling in long-term CD40-stimulated B cells promotes the transition from pre-malignant B cell expansions to monoclonal B cell lymphomas." (PMID 36110848, 2022).
gastric cancer (27 papers, 2009 to 2025). A primary or metastatic malignant neoplasm involving the stomach. "We still found that immunohistochemical expression of CD40 was significantly associated with gastric cancer cells metastasis and invasion." (PMID 19865524, 2009). "Importantly, the CD40 DNA methylation levels and CD40 expression (protein and mRNA) were associated with gastric cancer." (PMID 34492072, 2021). "In gastric cancer, ligation of CD40 by CD40L causes up-expression of VEGF by PI3K pathway." (PMID 25117071, 2014). "MEK/ERK and transcription factors AP-1 and NFκB are all involved in CXCL8 upregulation by IL-1β in gastric-carcinoma cells and by CD40 in human fetal microglia." (PMID 35806457, 2022). "The CXCL13/CXCR5 axis drives CD40+ MDSC migration to gastric cancer, leading to immune escape and tumor progression." (PMID 34947813, 2021). "Consistently, the transwell analysis confirmed the essential role of CXCR5-CXCL13 crosstalk in the migration of CD40+ MDSC toward gastric cancer." (PMID 26462153, 2015). "CD40 signalling in B cells is also known to promote germinal centre formation, and to be essential for the survival of many cell types including gastric cancer B cells under normal and inflammatory conditions." (PMID 26439692, 2015). "CD40 mutant expression in 78 cases of gastric cancer tissues, 10 cases of normal gastric tissues, and 10 cases of gastric adenoma tissues by immunohistochemical test." (PMID 24885116, 2014). "The present study aimed to examine the CD40 mutant expression in gastric cancer tissues and investigate the correlation of CD40 mutant expression and clinical outcome." (PMID 24885116, 2014). "The sCD40L/CD40 pathway activation in gastric cancer inhibited Fas- and drug-dependent apoptosis and also increased the motility of CD40-positive cancer cells, thus facilitating the formation of metastases, what was confirmed in humans." (PMID 25117071, 2014). "The results showed that as compared with healthy individuals, the maturation marker CD40 in MDDCs, IL-17A expression from T cells, and IL-10 expression from MDDCs were significantly lower in gastric cancer patients." (PMID 22526791, 2012). "To examine expression of CD40 in gastric cancer tissues, we tested the correlation of CD40 with lymphatic metastasis and tumors invasion." (PMID 19865524, 2009). "This indicated that CD40 molecule affected gastric cancer occurrence and development by regulating apoptotic index." (PMID 19865524, 2009). "In the gastric cancer group (56 patients), 19 patient (33.9%) had positive expression of CD40 and 10 patients (17.9%) had strong positive expression of CD40." (PMID 19865524, 2009). "CD40 is overexpressed in several carcinomas including cervical, ovarian and gastric cancers where its function remains largely unknown." (PMID 30562965, 2018). "Furthermore, more MDSC accumulated in the gastric cancers of WT mice when compared with KO mice, and the WT tumors mostly contained CD40+ cells." (PMID 26462153, 2015). "We believe that CD40 mutant plays an important role in mediating and regulating the biological behaviors of gastric cancer cells, and moreover may be a novel target for diagnosis and therapy of cancers." (PMID 24885116, 2014). "Positive CD40 mutant expression suggests a poorer prognosis of gastric cancer cases." (PMID 24885116, 2014). "We aimed to detect CD40 mutant expression and evaluate its clinical significance in gastric cancer." (PMID 24885116, 2014). "However, the mechanisms of the multifaceted roles of CD40 in gastric cancer are still not completely understood." (PMID 24885116, 2014). "However, the present preliminary study includes a great heterogenicity of the enrolled patients to evaluate the prognosis of patients with gastric cancer, and the role of CD40 mutant needs to be confirmed." (PMID 24885116, 2014).
gastric cancer (continued). "The positive CD40 mutant rate in gastric cancer was 55.1% (43/78)." (PMID 24885116, 2014). "However, the expression of CD40 co-stimulatory molecules was significantly lower in DCs from gastric cancer patients than in those from healthy individuals, both with and without H. pylori stimulation." (PMID 22526791, 2012). "In our present study, the observations of poor generation of the maturation marker CD40 on DCs following H. pylori infection and less IL-17 expression in gastric cancer patients indicated that immature DCs impaired the DCs’ capacity to induce autologous T-cell activation." (PMID 22526791, 2012). "Our work revealed significantly increased CD40 expression in gastric cancer." (PMID 19865524, 2009). "It is concluded that higher CD40 expression existed in expanding type tumors and could play an important role in clinical diagnosis of gastric cancer patients." (PMID 19865524, 2009). "The results indicated a high CD40 expression in gastric cancer tissues." (PMID 19865524, 2009). "The expression of CD40 in gastric carcinoma specimens was examined immuno-histochemically." (PMID 19865524, 2009). "Therefore, targeting CD40 or the CXCR5-CXCL13 axis could be a promising strategy for treating gastric cancer." (PMID 39840050, 2024). "Further analysis demonstrated that RORA expression in gastric cancer is positively correlated with immune checkpoint-related genes, including NRP1 and CD40." (PMID 40638694, 2025). "Research has shown that CD40 can regulate the expression of CXCR5 in MDSCs, influencing their recruitment and accumulation in gastric cancer." (PMID 39840050, 2024). "CD40, CAP2 proteins, and mRNAs expressions are closely related to prognosis, distant metastasis, and stage of patients with gastric cancer." (PMID 34386426, 2021). "In our study, we found that CD40, STAT3 and PD-L1 are the targets of miR-502-5p in gastric cancer cells by bioinformatics analysis and luciferase reporter assay." (PMID 32821248, 2020). "In addition, PD-L1 overexpression could restore the miR-502-5p-overexpression induced cellular effects whereas CD40/STAT3 overexpression could partially restore the miR-502-5p-overexpression suppressed gastric cancer cells proliferation, migration and invasion." (PMID 32821248, 2020). "The expressions of CD40 and STAT3 were decreased with the transient transfection of miR-502-5p in two gastric cancer cell lines by qRT-PCR and western blot." (PMID 32821248, 2020). "In this study, we examined the expression profile of CD40+ MDSC and investigated its potential involvement in MDSC recruitment to gastric cancer." (PMID 26462153, 2015). "Our results indicate that CD40 regulates the recruitment and accumulation of MDSC in gastric cancer by controlling CXCR5 expression in MDSC." (PMID 26462153, 2015). "To investigate the role of CD40 in MDSC cancer tissue infiltration, we established xenograft models using three different types of cancer cells: MFC for gastric cancer, LLC for lung cancer and RM-1 for prostate cancer." (PMID 26462153, 2015). "To study expression of CD40 and CD40L in gastric cancer tissue we assessed gastric cancer patients admitted to the Department of Gastroenterology of The First Affiliated Hospital of Soochow University and control subjects." (PMID 19865524, 2009). "This positive expression of CD40 revealed a significant (P < 0.05) correlation with lymphatic metastasis and tumor TNM stage in gastric cancer patients." (PMID 19865524, 2009). "For example, METTL3 activates dendritic cells and initiates activation of cytotoxic T lymphocytes by increasing m6A levels of CD40, CD80, and TLR4; METTL3 overexpression promotes gastric cancer progression (GC) and liver metastasis through angiogenic and glycolytic pathways." (PMID 35281520, 2022).
gastric cancer (continued). "Mechanically, these results indicated that miR-502-5p acted as a tumor suppressor by down-regulating PD-L1 expression via inhibiting the CD40/STAT pathway at the transcriptional level and binding to the 3′UTR of PD-L1 mRNA at the post-transcriptional level in gastric cancer." (PMID 32821248, 2020). "A significantly negative correlation was found between the CD40 expression and apoptotic index in the gastric cancer tissues (r = 0.263, P < 0.05)." (PMID 19865524, 2009). "The present study demonstrated that there was significant negative correlation between CD40 expression and apoptotic index in gastric cancer tissue." (PMID 19865524, 2009). "By downregulating CD40 and STAT3 expression, miR-502-5p can downregulate PD-L1 expression in gastric cancer (GC) cells." (PMID 35907881, 2022). "In leukemia, prostate, lung, pancreatic, colon, and gastric cancers, CXCL13 exhibits pro-cancer effects by recruiting B cells, CD68+ macrophages, regulatory B cells (Bregs), Treg, and CD40+ MDSCs, shaping an immune-suppressive TME to trigger tumorigenesis and tumor progression." (PMID 34947813, 2021). "Our results also suggest that CD40 mutant may be an important factor influencing gastric cancer patients’ survival time, which suggests that CD40 mutant may be an independent negative-regulating molecule influencing the prognosis of gastric cancer." (PMID 24885116, 2014). "The bladder carcinoma line, EJ, and the gastric carcinoma line, AGS, are CD40 receptor-positive, whilst the CD40-negative nasopharyngeal carcinoma line, HONE-1, was used as a negative control." (PMID 20211016, 2010). "Our work showed that there is negative correlation between CD40 expression and CD138 expression in gastric cancer." (PMID 19865524, 2009).